STX2 (syntaxin 2)
Description:
Essential for epithelial morphogenesis. May mediate Ca(2+)- regulation of exocytosis acrosomal reaction in sperm.
Synonyms: EPIM; STX2A; STX2B; STX2C; EPM
Tractability: Antibody: its Gene Ontology location is reachable by antibodies, with high confidence; UniProt predicts a signal peptide or a membrane-spanning region. PROTAC: ubiquitination databases record sites on it; its protein half-life has been measured.
Gene: Protein-coding gene on chromosome 12 (130,789,600 to 130,839,265, reverse strand). Ensembl gene ENSG00000111450.
Subcellular location: Membrane
Subcellular location (Human Protein Atlas): Vesicles; Nuclear membrane
Gene Ontology:
Molecular function: protein binding; structural molecule activity; calcium-dependent protein binding; SNARE binding; SNAP receptor activity
Biological process: cellular response to oxidative stress; cornified envelope assembly; epithelial cell development; acrosome reaction; animal organ morphogenesis; ectoderm development; exocytosis; synaptic vesicle fusion to presynaptic active zone membrane; intracellular protein transport; vesicle-mediated transport
Cellular component: basolateral plasma membrane; extracellular region; lamellipodium; plasma membrane; protein-containing complex; intracellular membrane-bounded organelle; presynaptic active zone membrane; membrane
Genetic constraint (gnomAD): Loss-of-function variants: 23 observed, 31.31 expected, observed/expected ratio (o/e) 0.73, 90% interval 0.53 to 1.04. The upper end of that interval is the gene's LOEUF score, 1.04, which puts it in group 4 of 6, group 1 being the genes least tolerant of losing a copy. Missense variants: 285 observed, 324.76 expected, observed/expected ratio (o/e) 0.88, 90% interval 0.8 to 0.97. Synonymous variants: 110 observed, 106.98 expected, observed/expected ratio (o/e) 1.03, 90% interval 0.88 to 1.21.
Homologues: Orthologues: chimpanzee STX2 (99% identical), macaque STX2 (99% identical), pig STX2 (95% identical), dog STX2 (92% identical), rabbit STX2 (90% identical), mouse Stx2 (90% identical), rat Stx2 (89% identical), guinea pig STX2 (85% identical), tropical clawed frog stx2 (67% identical), zebrafish stx2b (62% identical), Drosophila melanogaster Syx1A (59% identical), Caenorhabditis elegans unc-64 (55% identical), and 1 more. Paralogues in human: STX1B (64% identical), STX1A (64% identical), STX3 (64% identical), STX4 (45% identical), STX11 (31% identical), STX19 (28% identical), STX5 (27% identical), STX12 (23% identical), STX16 (23% identical), STX7 (21% identical), STX17 (17% identical), TSNARE1 (15% identical).
Diseases named in the same sentence as STX2 in open-access papers:
STX2 is named in the same sentence as 80 diseases in open-access papers, as found by Europe PMC text mining. Sharing a sentence is not in itself a finding about the gene and the disease. The quoted sentences say what the papers report.
hemolytic-uremic syndrome (75 papers, 2006 to 2026). Acute kidney injury associated with microangiopathic hemolytic anemia and thrombocytopenia. "cDDLAMP was developed targeting 3 common STEC’s virulence genes (stx1, stx2, and eae) that are associated with serious human illnesses such hemorrhagic colitis and hemolytic-uremic syndrome." (PMID 40267081, 2025). "The main virulence markers of E. coli O157:H7 are Shiga toxin (Stx1 and Stx2) genes, which are commonly linked to severe diseases such as hemolytic-uremic syndrome and hemorrhagic colitis." (PMID 41231310, 2025). "It is less likely that Stx1 will produce diseases in humans, while Stx2 is more likely to cause diseases like hemorrhagic colitis (HC) and hemolytic-uremic syndrome (HUS)." (PMID 38165462, 2024). "Epidemiological and clinical investigations have indicated that the presence of stx2 is crucial for causing hemolytic uremic syndrome (HUS), and strains carrying additional VAGs can lead to severe illnesses." (PMID 39204259, 2024). "STEC strains that carry the gene for Stx2 cause more severe diseases, such as hemolytic uremic syndrome, than strains that carry Stx1 or both Stx1 and Stx2." (PMID 38633705, 2024). "E. coli O157:H7 strains either express Stx1, Stx2, or both genes, however the more toxic of the two genes is Stx2 which causes hemorrhagic colitis and hemolytic uremic syndrome." (PMID 38124028, 2023). "The stx2 and eae genes together are often found to be associated with hemolytic uremic syndrome and are considered a risk factor for high virulence." (PMID 37999503, 2023). "Shiga toxins 1 and 2 (Stx1 and Stx2, respectively) differ in their virulence and host specificity, with Stx2 being most commonly associated with severe illnesses (hemolytic uremic syndrome (HUS), hospitalization, and bloody diarrhea) in humans." (PMID 37317259, 2023). "Both stx1 and stx2 are related to infections in humans, although stx2 toxin is more virulent as it is responsible for causing hemolytic uremic syndrome in humans." (PMID 36766304, 2023). "The stx gene is associated with edema disease in swine and hemolytic-uremic syndrome in humans and the receptor for stx2 is globotriosyl ceramide, which is found in both humans and pigs." (PMID 36658572, 2023). "Most of our STEC harboured stx2 which is strongly associated with haemorrhagic colitis and haemolytic uraemic syndrome in humans." (PMID 35130987, 2022). "STEC virulence involves two shiga toxins, encoded by the stx1 and stx2 genes within the lambdoid prophages, which inhibit protein synthesis, leading to diarrhea and the potential for bloody diarrhea and hemolytic uremic syndrome (HUS)." (PMID 33207846, 2020). "Stx2 toxin is more virulent than Stx1 because that toxin is responsible for causing Hemolytic Uremic Syndrome in humans." (PMID 32258064, 2020). "The Stx2 converting phage of E. coli O157:H7 and other related Shiga toxigenic E. coli (STEC) encodes the Stx2 protein, an important virulence factor causing lysis of host cells and contributing to hemolytic uremic syndrome." (PMID 30934749, 2019). "Stx2-producing strains are more virulent than Stx1-producing ones and are frequently associated with hemolytic uremic syndrome (HUS), a thrombotic microangiopathy characterized by thrombocytopenia, hemolytic anemia, and acute renal failure." (PMID 30513821, 2018). "A previous study reported that stx2 is the most important virulence factor and most of hemolytic-uremic syndrome cases in humans are caused by STEC strains harboring stx2 gene." (PMID 29184374, 2017). "Shiga toxin (Stx) production, especially Stx2, has been implicated as an important factor in causing severe disease and hemolytic uremic syndrome (HUS)." (PMID 29121863, 2017). "STEC strains that cause hemolytic uremic syndrome (HUS) in humans more often produce Stx2, and there are several subtypes of stx2 that are responsible for differences in cytotoxicity (7, –, 9)." (PMID 27037122, 2016).
hemolytic-uremic syndrome (continued). "Some STEC strains produce Shiga toxin 1 (Stx1) and/or Shiga toxin 2 (Stx2) or variants of either toxin, which are critical for the development of hemorrhagic colitis (HC) or hemolytic uremic syndrome (HUS)." (PMID 25938272, 2015). "Strains carrying Stx2 are considered more virulent and related to the majority of outbreaks, besides being usually associated with hemolytic uremic syndrome in humans." (PMID 25790467, 2015). "The high incidence of stx2 strains combined with eaeA and E-hyl genes that we found in wild cervid feces is associated with severe human disease, such as hemolytic uremic syndrome." (PMID 24349083, 2013). "Shiga toxins 1 and 2 (Stx1 and Stx2) are bacteriophage-encoded proteins that have been associated with hemorrhagic colitis, hemolytic uremic syndrome and other severe disease conditions." (PMID 18053224, 2007). "Enterohemorrhagic E. coli that produce Stx2 are more likely to cause hemolytic uremic syndrome than are Stx1 producers." (PMID 18053224, 2007). "Moreover, there are over 400 described STEC serotypes that express one or more of stx1 genes and stx2 genes and among those, around 100 serotypes have been described as causing illness in humans, with hemolytic uremic syndrome (HUS) being deadly." (PMID 41433308, 2025). "Moreover, E. coli 8501 was of serotype O8:H19, characteristic of porcine stx2-producing E. coli, which is associated with mild disease and has occasionally caused hemolytic uremic syndrome in the Netherlands." (PMID 40160473, 2025). "Both the stx1 and stx2 genes are associated with severe symptoms like hemolytic uremic syndrome; these vary in the target organ and can cause different pathologies depending on the animal host; for example, in humans, stx2 gene expression is more often related to clinical complications than stx1." (PMID 37508064, 2023). "The findings of most of these studies were in agreement with previous reports indicating that EHEC strains possessed stx, stx2, hlyA, and eaeA gene determinants that enhance their potential to cause infections such as diarrhea, hemorrhagic colitis (HC) and hemolytic uremic syndrome (HUS) in humans." (PMID 31608246, 2019). "In general, stx2 strains are 1,000 times more cytotoxic in humans than stx1 strains or strains carrying both stx1 and stx2; presence of stx2 is also the most important virulence factor associated with severe human disease, such as hemolytic uremic syndrome." (PMID 24349083, 2013). "Shiga toxin 2 (Stx2), one of two Stx liberated by Stx-producing Escherichia coli, is composed of an A subunit monomer and a B subunit pentamer, and is directly linked with hemolytic uremic syndrome in children." (PMID 20334660, 2010). "The most pathogenic serotype of E. coli is O157:H7, which produces Shiga toxins (stx1 and stx2) that cause severe hemolytic-uremic syndrome (HUS) in humans." (PMID 38358989, 2024). "STEC produces Shiga toxins (stx1 or stx2) that can cause local colon damage, leading to hemorrhagic colitis (HC), and complications such as hemolytic-uremic syndrome (HUS) in humans." (PMID 36355898, 2022). "Notably, Shiga toxins 1 and 2 (Stx1 and Stx2) encoded by stx1 and stx2 can result in gastrointestinal symptoms, such as diarrhea and hemorrhagic colitis, and may also progress to a hemolytic uremic syndrome, a severe sequela of this infection." (PMID 33101241, 2020). "An additional 4 patients (4 survivors) were diagnosed with infection-associated hemolytic-uremic syndrome (IA-HUS) based on the detection of STX1 or STX2 genes using Polymerase Chain Reaction (PCR) testing for enterohemorrhagic Escherichia coli (EHEC) from stool specimens." (PMID 40990987, 2025). "EHEC, especially serotype O157:H7, produces potent Shiga-like toxins (Stx1 and Stx2), which can result in life-threatening conditions such as haemorrhagic colitis and hemolytic uremic syndrome (HUS)." (PMID 40426498, 2025).
hemolytic-uremic syndrome (continued). "The pathology of STEC infection derives from two exotoxins—Shiga toxin 1 (Stx1) and Shiga toxin 2 (Stx2)—that are secreted by STEC in the gut, from where they are systemically absorbed, causing severe kidney damage leading to hemolytic uremic syndrome (HUS)." (PMID 36290479, 2022). "Generally, the likelihood of developing hemolytic uremic syndrome (HUS) due to the stx2 gene depends on STEC." (PMID 35407047, 2022). "The primer sets used in this study targeted a region common for both the stx1 and stx2 genes found in the EHEC strain, which causes hemolytic uremic syndrome and hemorrhagic colitis in humans." (PMID 25659126, 2015). "In a previous study, we analyzed 23 STEC O26 strains carrying the stx2 gene only, which were isolated in France between 2010 and 2013 from hemolytic-uremic syndrome (HUS) patients." (PMID 26227606, 2015). "C3a activation of endothelial cells thus forms an amplification loop of complement activation, implicated in microvascular thrombosis, including in a mouse model of Shiga-toxin (Stx2)/LPS induced hemolytic uremic syndrome (HUS)." (PMID 26074922, 2015). "Release of STX1 and STX2 by EHEC and EAEC strains causes hemorrhagic colitis and hemolytic uremic syndrome, and is highly correlated with mortality." (PMID 23372726, 2013). "Hemolytic uremic syndrome (HUS) leading to acute kidney failure, is a condition linked to the production of primarily Shiga toxin 2 (Stx2) by some E. coli serotypes." (PMID 22655967, 2012). "The clinical significance with regard to the risk of developing severe diseases as a consequence of an EHEC infection varies considerably with the different Stx1- and Stx2-subtypes, which are associated with the EHEC-caused hemolytic-uremic syndrome (HUS) to varying degrees." (PMID 35805890, 2022). "All the bovine O104:H7 strains investigated in this study were negative for stx2, which is more frequently associated with human illnesses, particularly hemolytic uremic syndrome, than stx1." (PMID 29708991, 2018). "Shiga toxin 2 (Stx2) is a major virulence factor in infections with Stx-producing Escherichia coli (STEC), which can cause serious clinical complications in humans, such as hemolytic uremic syndrome (HUS)." (PMID 26903273, 2016). "An outbreak of Shiga Toxin 2 (Stx-2) producing enterohemorrhagic and enteroaggregative E.coli (EAHEC) O104H4 infection in May 2011 caused enterocolitis and an unprecedented high 22% rate of hemolytic uremic syndrome (HUS)." (PMID 24086391, 2013). "The increase in Stx2-production by ON-2011 following mitomycin C treatment may or may not be related to the high rates of hemolytic uremic syndrome associated with the German outbreak strain." (PMID 22649523, 2012). "Reports on clinical STEC have suggested that stx2-positive isolates are more virulent and frequently incriminated in severe human disease including hemorrhagic colitis and hemolytic uremic syndrome in comparison to STEC isolates carrying stx1 or both stx1 and stx2." (PMID 35622599, 2022). "Shiga toxin-producing E. coli was found to harbor different genes such as eae, aaiC, aggR, stx2a, stx1, and stx2; however, eae, stx1 and stx2 and stx2a genes were found to be involved in a wide spectrum of gastrointestinal disorders ranging from non-bloody diarrhea to hemolytic uremic syndrome." (PMID 41596850, 2026). "Although there was some similarity in the virulence gene profile of human and bovine O104 strains, the key virulence genes, such as stx2 responsible for more serious infections, including hemolytic uremic syndrome, was absent in bovine strains, but present in human clinical and outbreak strains." (PMID 29708991, 2018).
acute renal failure (17 papers, 2009 to 2026). "Hemolytic uremic syndrome (HUS), the main cause of acute renal failure in early childhood, is associated with infections by Escherichia coli strains producing Shiga toxin 2 (Stx2)." (PMID 40740497, 2025). "In CD1KO mice, which lack natural killer T (NKT) cells, Stx2-induced pathologies such as weight loss, renal failure, and death were delayed." (PMID 25904903, 2015). "HUS is a leading cause of renal failure in otherwise healthy children and Shiga toxin type 2 (Stx2) is often associated with severe symptoms of STEC infection." (PMID 25904903, 2015). "In this model, Stx2 causes apoptosis of medullary and cortical tubular cells in the kidneys, and leads to renal failure due to the loss of functioning collecting ducts." (PMID 22655967, 2012). "Stx2 in the kidneys of mice is toxic and causes apoptosis of medullary and cortical tubular cells, and renal failure due to the loss of functioning collecting ducts." (PMID 22655967, 2012). "Mice injected with Stx2/LPS develop a HUS phenotype (thrombocytopenia, glomerular capillary thrombosis, and acute kidney injury) with excessive glomerular C3 deposits and injury and loss of podocytes." (PMID 32447506, 2020). "The assessment of lipid peroxidation has been determined in a model of renal failure following intravenous administration of Stx2." (PMID 30732602, 2019). "E. coli O157:H7 strains carrying Stx2 are more virulent and are more frequently associated with HUS, which is the most common cause of renal failure in children in the US." (PMID 25938272, 2015). "CXCL1 and CXCL2, were recently shown to be essential for neutrophil recruitment which is key to acute renal failure developing in Stx2-challenged LPS-treated mice." (PMID 21731756, 2011). "Shiga toxin (Stx) belongs to a family of AB5 toxins classified as Stx1 and Stx2, and although both toxins could be present in EHEC O157:H7 isolates, Stx2 is often associated with severe disease and development of renal failure." (PMID 35044806, 2022). "Hemolytic uremic syndrome (HUS) is an illness characterized by a triad of events that include nonimmune haemolytic anaemia, thrombocytopenia and acute renal failure caused by Shiga toxin 2 (Stx2) from enterohemorrhagic Escherichia coli (EHEC)." (PMID 30732602, 2019). "CXCL2, CCL5, and TNFα were also reduced in HuSAP+ mice (relative to WT) 48 hours after Stx2 treatment and therefore may be crucial for the inflammatory pathology leading to acute renal failure." (PMID 21731756, 2011). "Extracellular vesicles promote the development of renal failure associated with EHEC infection by exposing a prothrombotic surface on their membranes, by participating in hemolysis and, most importantly, by transferring the main virulence factor Stx2 to the kidney." (PMID 34073384, 2021). "Therefore, we hypothesize that NKT cells may accelerate progression to renal failure during STEC infection through Stx2-effects on renal endothelium and podocytes that potentiate NKT-cell activation and result in increased inflammatory signaling." (PMID 25904903, 2015). "We hypothesize that during human EHEC infection, both Stx2-containing OMVs and free Stx2 translocate from the intestine to the bloodstream and enter the kidneys, where they injure glomerular endothelial cells and tubular epithelial cells, which leads to acute kidney failure." (PMID 41368436, 2025). "No Stx2 was detected in microvesicles from the controls (n = 10) or patients with acute renal failure (n = 2), as expected." (PMID 25719452, 2015). "As a control, no binding of the anti-stx2 antibody was detected on blood cells from the three patients with acute renal failure indicating that antibody binding was not due to cell changes related to acute renal failure." (PMID 19750223, 2009).
acute renal failure (continued). "Porubsky and colleagues demonstrated, using transgenic mice lacking Gb3 in tubular epithelial cells, that the tubular absence of Gb3 protected mice against Stx2-mediated tubular injury, acute kidney failure, and death observed in wild-type mice that carried Gb3 on tubular epithelial cells." (PMID 41368436, 2025).
renal failure (11 papers, 2012 to 2025). "Each food strain has either one or both stx1 and stx2 genes, which are often the major contributors resulting in HUS and kidney failure in some cases." (PMID 38003767, 2023).